EGFR (epidermal growth factor receptor)
Diseases named in the same sentence as EGFR in open-access papers (continued):
Sharing a sentence is not in itself a finding about the gene and the disease.
tumor (continued). "Our findings suggest EGFR inhibitors could serve as a promising therapeutic option for managing recurrent WT patients; however, further investigation is required to fully elucidate the mechanisms driving the upregulation of EGFR in Scissor+ tumor cells." (PMID 40098972, 2025). "This marked elevation suggests that while gefitinib effectively targets EGFR signaling, it may concurrently activate compensatory or stress-related pathways that drive IL-6 production—a cytokine known to support tumor growth, immune evasion, and therapeutic resistance." (PMID 41401147, 2025). "Thus, in a hamster model, increased EGFR expression was also demonstrated predominantly in the bile duct epithelium 3 and 6 months postinfection, which was accompanied by an increase in the degree of neoplasia." (PMID 40732668, 2025). "However, the findings in studies employing EGFR mutant tumor models remain equivocal." (PMID 40130724, 2025). "Additionally, since treatment regimens were chosen by each investigator, anti-EGFR antibodies may have been more commonly used in patients with higher tumor burdens or poorer prognoses, potentially influencing the observed outcomes." (PMID 39941768, 2025). "Despite these achievements, recent studies have shown that treatment of EGFR TKIs leads to the development of acquired resistance through target gene mutations, activation of alternative RTK signaling pathways, histological transformation, or intra-tumor heterogeneity." (PMID 39948411, 2025). "Similarly, ERBB2 gene amplification throughout the tumor may confers resistance to EGFR-targeted monoclonal antibodies in CRC." (PMID 40828885, 2025). "This interaction between the BTI microenvironment and the host immune system may provide valuable insights into tumor behavior under EGFR-TKI treatment, suggesting that the BTI region holds more predictive value than features derived solely from the tumor mass of BM." (PMID 40438144, 2025). "However, the question remains: how can tumor prognosis be predicted more accurately in cancers without EGFR mutations or other mutation-driven genes?" (PMID 40124619, 2025). "In addition, internalization of the EGFR compound complex facilitates reliable localization of the radioisotope and fluorescent dye in the intended target region, allowing precise delineation of tumor margins." (PMID 40005958, 2025). "Similarly, EGFR amplification intensifies oncogenic signaling pathways that facilitate cell proliferation and resistance to typical therapies, thus acting as a marker of aggressive tumor behavior." (PMID 40058218, 2025). "Furthermore, they can be surface-modified with targeting molecules, such as antibodies, peptides, or folate, to bind tumor-associated receptors like HER 2, EGFR, the transferrin receptor, and αvβ3 integrins, enhancing targeted delivery and minimizing off-target toxicity." (PMID 40869364, 2025). "It is conceivable that more aggressive regimens, combining CT with anti-angiogenic agents or monoclonal antibodies targeting epidermal growth factor receptor (EGFR), could lead to higher rates of tumor regression, including in patients with poor responses to CRT." (PMID 40724514, 2025).
tumor (continued). "The ability of LAPTM4B to modulate key signaling pathways, such as PI3K/AKT and EGFR, and affect autophagy and chemoresistance, and its ability to interact with autophagy-associated proteins and ceramides, further illustrates the complexity of the role of LAPTM4B in tumor cell survival." (PMID 40231269, 2025). "However, 46 of 246 (19%) tumours with this 5q gain are absent of either an EGFR mutation or copy number gain." (PMID 41509216, 2025). "Aqp5-induced changes in tumor biological behavior may be regulated by a variety of signaling pathways leading to cell transformation, including tyrosine kinase Src family, epidermal growth factor receptor, Wnt signaling pathway and Erk1/2 mediated signal transduction." (PMID 40760228, 2025). "Importantly, restoration of CaM expression could effectively rescue curcumin-induced EGFR downregulation and tumor growth inhibition." (PMID 40447190, 2025). "For example, radiomic profiles linked to PD-L1 (programmed death ligand 1) expression, tumor-infiltrating lymphocytes (TILs), or EGFR mutation status (common in NSCLC-derived metastases) may predict response to anti-PD-1/PD-L1 inhibitors or EGFR tyrosine kinase inhibitors (TKIs)." (PMID 40722321, 2025). "Moreover, continuous EGFR-TKI treatment induced the upregulation of MCAM expression in tumours." (PMID 40713600, 2025). "Because the epidermal growth factor receptor (EGFR) is highly expressed in nearly all carcinomas and capable of receptor recycling after endocytosis, we sought to determine whether an EGFR-targeting ligand could enable tumor-directed chimera delivery." (PMID 40762837, 2025). "Therefore, SPINK-mediated signalling in cancer involves defined and receptor-specific interactions with EGFR and downstream cascades, as well as influence over inflammation, metabolism, and genomic stability, functioning as both an oncogene and tumor suppressor." (PMID 40872585, 2025). "Additionally, genetic modifications that incorporate surface-displayed ligands such as folate or epidermal growth factor receptor (EGFR)-targeting peptides have shown promising results in preclinical models by improving the selectivity and accumulation of EVs within the tumor microenvironment." (PMID 40284502, 2025). "Indeed, ctDNA levels correlate with early tumor response and can predict resistance to anti-EGFR, anti-HER2, and BRAF-targeted therapies, helping to identify patients who may benefit from reintroducing anti-EGFR therapy after resistant clones have disappeared." (PMID 40508077, 2025). "Moreover, studies integrating scRNA-seq data identified that the infiltration of CXCR1+ neutrophils—capable of promoting tumor cell resistance to third-generation EGFR-TKIs via activation of the TNF-α/NF-κB signaling pathway—was closely associated with EGFR-TKI resistance." (PMID 40003951, 2025). "Finally, T-cytotoxic lymphocytes (CD8+) and tumor-associated macrophages (CD163+) were evaluated in samples with EGFR and KRAS mutations, ALK rearrangements and LUAD with no genetic findings." (PMID 40809430, 2025). "Similarly, the proportion of EGFR+ tumor cells had a predictive AUC of 90.1% for EGFR amplification, with the best cutoff point at 14.3%, and the proportion of CDKN2A+ tumor cells had a predictive AUC of 79.4% for CDKN2A deletions with the best cutoff point of 0.5%." (PMID 40264576, 2025). "Additionally, CIN-dependent cGAS–STING signaling activity may influence the tumor immune environment, particularly with regard to inflammatory cell infiltration, which may consequently influence the efficacy of EGFR-TKI therapy." (PMID 40136696, 2025). "Thus, radiolabeled peptides that bind to EGFR for tumor imaging and therapy are of great interest." (PMID 39860082, 2025). "Notably, this bacterium has been associated with resistance to cetuximab—an anti-EGFR monoclonal antibody—by activating the PI3K/AKT and JAK/STAT3 signaling pathways, resulting in elevated half-maximal inhibitory concentrations (IC50) in infected tumor cells." (PMID 40959527, 2025).
tumor (continued). "Additionally, the application of ETS and DpR may need to be tailored to specific populations, as differences in the mechanisms of tumor shrinkage between EGFR‐TKIs and immune therapies could influence the predictive performance of ETS and DpR." (PMID 40959866, 2025). "Targeted therapies (such as anti-angiogenic drugs and EGFR inhibitors) inhibit tumor progression by specifically blocking tumor growth signals or angiogenesis, but they are prone to developing resistance and may not sufficiently sensitize tumors to radiotherapy." (PMID 41450947, 2025). "Notably, immunohistochemical (IHC) staining with anti-EGFR antibodies revealed a significant reduction in EGFR expression in tumor tissues from NSG mice engrafted with USP11-KO HCT-15 cells compared to those with control HCT-15 cells (USP11-KO HCT-15 vs. Ctrl HCT-15)." (PMID 41419456, 2025). "This lack of efficacy may be attributed to factors such as low PD-L1 expression, low tumor mutational burden (TMB), and the upregulation of an immunosuppressive tumor microenvironment (TME), which collectively put EGFR-mutant patients at a disadvantage when receiving ICI treatment." (PMID 41357203, 2025). "In summary, this study showed that EGFR-restricted CAR-T cells showed fairly good efficacy in cytoreducing the tumor mass following intratumoral injection; however, the absence of spreading into the systemic circulation could correlate with a poor response on any distant metastases." (PMID 40647513, 2025). "Interestingly, we found Lac significantly reduce the tumor burden in WT EGFR-DEL mice." (PMID 39979425, 2025). "Therefore, several previously unrecognized mechanisms in the tumor microenvironment may greatly contribute to the constitutive activation of EGFR." (PMID 40940319, 2025). "In accordance with this, EGFR mutations are the events most significantly associated with NSD trajectories across all LUAD samples (OR for enrichment in NSD = 88.9, FDR = 2.2×10−54), and found exclusively in NSD tumours when considering only NS-LUAD (FDR = 1.5×10−26)." (PMID 41509216, 2025). "Indeed, petosemtamab has been shown to be more effective than cetuximab in various preclinical models of cancer that express both LGR5 and EGFR, in terms of inhibiting organoid growth in vitro and inhibiting xenograft tumor growth or the outgrowth of metastases in vivo." (PMID 40427162, 2025). "In this study, we evaluated the potential of early tumor shrinkage and depth of response as surrogate endpoints for overall survival and postprogression survival, defined as survival following first-line therapy, in patients treated with chemotherapy plus an anti-EGFR antibody or bevacizumab." (PMID 40280867, 2025). "Notably, in A549 tumor-bearing BALB/c nude mice, intravenous administration of Ctx-CMA surpassed conventional cetuximab therapy, exhibiting both enhanced tumor growth suppression and a significant reduction in EGFR protein levels compared to control groups (IgG-CMA and Ctx alone)." (PMID 40724826, 2025). "The fact that this relationship can be detected in TCGA‐PRAD tumor samples, expected to better represent the heterogeneity of each molecular subtype, strongly supports that the observed regulatory interaction between EGFR/STAT3 and ETV1 is likely to persist in vivo, independently of the tumor stage." (PMID 40808640, 2025). "PLCH1 expression showed a strong positive correlation with EGFR-related pathways, including KEGG_TGFA_EGFR_PLCG_PKC_SIGNALING_PATHWAY (R = 0.35, P < 2.22e-16) and KEGG_EGF_EGFR_PLCG_ERK_SIGNALING_PATHWAY (R = 0.27, P < 2.22e-16), which are crucial for tumor cell proliferation and migration." (PMID 40519297, 2025).
tumor (continued). "Furthermore, a subset of patients, particularly those with high tumor burden, brain metastases, or poor performance status, may exhibit suboptimal initial responses or rapid progression on standard-dose EGFR-TKI therapy." (PMID 41479790, 2025). "Selective inhibitors of various kinases, including cyclin-dependent kinases 4 and 6 (CDK4/6), epidermal growth factor receptor (EGFR) tyrosine kinase, and aurora kinase A have shown promise in various malignancies by inhibiting cell cycle progression and suppressing the growth of 3D tumor spheroids." (PMID 41226237, 2025). "Furthermore, tumor tissue EGFR protein levels were elevated in patients with both genotypes." (PMID 40438325, 2025). "Additionally, as mentioned in the literature, while brigatinib is effective against osimertinib-resistant EGFR mutants, tumor relapse, as observed in this case, suggests that additional resistance mutations might emerge." (PMID 40422529, 2025). "From a therapeutic perspective, targeting the molecular components of the “Black” module, such as WNT5A, EPHA2, and EGFR, could offer promising strategies to counteract tumor invasiveness and overcome drug resistance, particularly in Cluster B patients, who may be more responsive to such inhibitors." (PMID 41465101, 2025). "Hence, we speculate that EUDAL/EGFR/STAT3 signaling-induced autophagy may lead to drug resistance in these tumor cells." (PMID 40940319, 2025). "However, conducting tumor rebiopsies to detect the T790M mutation in patients with advanced NSCLC who have been treated with EGFR‐TKIs is not always feasible in clinical practice." (PMID 41221800, 2025). "However, knowledge regarding the causal relationships between tumor hypoxia and noncanonical EGFR activation is limited." (PMID 40940319, 2025). "The growth of GlcT mutant clones appeared to cause a general increase of EGFR and JAK/STAT activities within the intestinal epithelium, as many differentiated cells also exhibited EGFR or JAK/STAT signaling activation, which is likely due to stress responses induced by tumor growth." (PMID 41431871, 2025). "The EGFR exon 19 deletion was detected in the resected tumor, while the T790M mutation was absent." (PMID 40051929, 2025). "Therefore, EBP has become a promising vector for EGFR-targeting Gd chelates to improve the specificity and sensitivity of contrast-enhanced MRI in clinical tumor diagnosis, enabling the application of molecule-targeted drugs in vivo for noninvasive tumor subtyping and treatment." (PMID 41325799, 2025). "This suggests nCRT may shift EGFR distribution, hindering tumor visualization." (PMID 40563608, 2025). "Tumor mutation burden (TMB), programmed cell death ligand 1(PD-L1) expression, and the infiltrations of some vital cell types in tumor immune microenvironments were considered close to response to ICI, while how they regulated patients with EGFR 20ins mutations responding to ICI were still unclear." (PMID 41162774, 2025). "However, it is important to note that these changes were largely independent of age, sex, histologic classification, epidermal growth factor receptor mutation and, notably, tumor PD-L1 expression." (PMID 40307573, 2025). "In the BaF3 (EGFRDel746-750/T790M/C797S) xenotransplantation model, TQB3804 inhibits the growth of the transplanted tumour model by inhibiting phosphorylated EGFR (p-EGFR), phosphorylated AKT (p-AKT), and phosphorylated extracellular signal-regulated kinase (p-ERK) targeting EGFR tertiary mutation." (PMID 40172117, 2025). "Similarly, in non-small cell lung cancer (NSCLC), tumor cells resistant to epidermal growth factor receptor (EGFR) inhibitors (erlotinib, osimertinib) depend heavily on the NRF2-mediated antioxidant response to maintain low intracellular ROS levels via upregulation of GPx4 and SOD2." (PMID 41009046, 2025).
tumor (continued). "Given that one of the primary gene regulatory functions of circRNAs is to impact tumor pathogenesis by serving as competing endogenous RNAs (ceRNAs) through their interaction with miRNAs, we explored the ability of circ-EGFR to act as a molecular sponge for miRNAs in CRC." (PMID 41214390, 2025). "Biomarkers of ICI therapy, such as programmed cell death ligand 1 (PD-L1) and tumor-infiltrating lymphocytes (TILs), are not biomarkers in patients with EGFR mutations, and the specificity of the tumor microenvironment has been suggested as the reason for this." (PMID 39280252, 2024). "We found that not all ex20ins mutations reported by cobas EGFR test v2 could be validated by Sanger sequencing even using surgical specimens with high tumor contents." (PMID 38687753, 2024). "Thus, antibody‐IR700 mainly accumulates in tumor with high expression of EGFR." (PMID 38888415, 2024). "By analyzing high-throughput data extracted from standard MRI scans, radiomics allows for the detailed characterization of tumor phenotype and microenvironment, offering a promising avenue for predicting EGFR mutation status without the need for invasive procedures." (PMID 39834943, 2024). "In a different study, miR-133a-3p was shown to act as a tumor suppressor and to inhibit the proliferation, differentiation, and motility of cancer cells via different mechanisms, such as targeting several oncogenes, targeting the EGFR/Akt signaling pathway, and inhibiting IGF1R expression." (PMID 38793064, 2024). "The development of these mutations following anti-EGFR targeted treatment, can be a consequence of alterations rising from pre-existent KRAS altered clones, or due to new mutations derived from stress conditions induced by targeted therapy to the tumor and tumor microenvironment." (PMID 38711991, 2024). "Additionally, concerning how phosphorylated Dicer regulates specific miRNAs, previous literature indicates that under hypoxic conditions expected in the tumor microenvironment, the epidermal growth factor receptor (EGFR) can phosphorylate argonaute (AGO) at Y393, changing its structure." (PMID 39519347, 2024). "In addition, combining anti-EGFR antibodies with neoadjuvant chemotherapy has been shown to remodel the tumor microenvironment by increasing cytotoxic T cells and decreasing immunosuppressive regulatory T cells and M2 macrophages, resulting in higher remission rates." (PMID 39796003, 2024). "Since the identical EGFR mutation patterns occurred in the squamous cell carcinomatous and the adenocarcinomatous components of ASC, It may be the proportion of two tumor components in EGFR mutant ASC patients that determines the efficacy of EGFR-TKI in EGFR mutant ASC patients." (PMID 39026979, 2024). "Additionally, ATRX mutations, EGFR (epidermal growth factor receptor) alterations, CD70, CD147, CDKN2A deletions, exosomes, cfDNA (cell-free DNA), ctDNA (circulating tumor DNA), and CTCs (circulating tumor cells) stand out as significant markers." (PMID 38732975, 2024). "However, clinical observations have contradicted this hypothesis, as most patients have shown a good response to EGFR-TKIs for extended periods, and greater tumor growth has been observed at the time of SCLC diagnosis." (PMID 39513032, 2024). "Epidermal growth factor receptor (EGFR) may mediate specific pathways to impact tumor cells." (PMID 39568569, 2024). "However, ODZ1 has not been linked to the epidermal growth factor receptor (EGFR), a key player in tumor malignancy in several cancer types, including GBM, and a target for therapeutic interventions." (PMID 38727302, 2024).